MCOLN1 (mucolipin TRP cation channel 1)
Diseases named in the same sentence as MCOLN1 in open-access papers (continued):
Sharing a sentence is not in itself a finding about the gene and the disease.
MCOLN1 also shares sentences with these, for which no sentence is quoted: Alzheimer disease (11 papers); breast carcinoma (9); amyotrophic lateral sclerosis (6); metastatic melanoma (6); Fabry disease (5); hepatocellular carcinoma (4); pancreatic ductal adenocarcinoma (4); viral infection (4); bladder cancer (3); cognitive deficits (3); liver cancer (3); Lysosomal disease (3); retinal degeneration (3); triple-negative breast carcinoma (3); Batten disease (2); Bladder urothelial carcinoma (2); ceroid lipofuscinoses (2); channelopathies (2); depression (2); developmental delay (2); genetic disorder (2); head and neck squamous cell carcinoma (2); HIV-1 infection (2); myocardial ischemia (2); Niemann-Pick disease (2); ovarian carcinoma (2); Parkinson (2); sphingolipidoses (2); anaemia (1); Ataxia (1).
A further 51 diseases each share a sentence with MCOLN1 in 1 paper.